APP (amyloid beta precursor protein)
Diseases named in the same sentence as APP in open-access papers (continued):
Sharing a sentence is not in itself a finding about the gene and the disease.
Cognitive impairment (continued). "Although Nr3c1ki/ki-APP/PS1 mice displayed accelerated age-related cognitive deficits, other indicators of AD-like pathology by neuroimaging were unchanged." (PMID 35733193, 2022). "Clearance of APP 586–695 in 5xFAD mice or blockage of AEP truncation of APP ameliorates Aβ pathology and cognitive impairments." (PMID 36296969, 2022). "Losartan and valsartan decrease Aβ peptide oligomerization in primary neuronal cultures and reduce cognitive impairment in Tg2576 AD transgenic mice, expressing the human 695-aa isoform of the amyloid precursor protein gene (APP)." (PMID 35207180, 2022). "Here, it is found that young osteocyte, the most abundant cells in bone, secretes extracellular vesicles (OCYYoung‐EVs) to ameliorate cognitive impairment and the pathogenesis of AD in APP/PS1 mice and model cells." (PMID 35508803, 2022). "Accordingly, we obtained results from the APP‐KI mouse model of AD that exhibits endogenous expression of APP and cognitive deficits and showed their relevance to human brain samples from AD patients and age‐matched controls." (PMID 35181976, 2022). "Here, we have shown that the reduction of VGSC α‐subunit Nav1.6 (by injecting adeno‐associated virus (AAV) with short hairpin RNA (shRNA) into the hippocampus) rescues cognitive impairments and attenuates synaptic deficits in APP/PS1 transgenic mice." (PMID 35353937, 2022). "ML264 ameliorated the cognitive deficits and slowed down APP amyloidogenic cleavage in APP/PS1 mice." (PMID 35883144, 2022). "GRINA3, specifically, interacts with acamprosate, which has been associated with decreased incidence of dementia in population studies and has been seen to alleviate cognitive defects in amyloid precursor protein (APP) transgenic mice." (PMID 36268052, 2022). "In this study, 10-month-old male APP/PS1 mice were subjected to long-term voluntary wheel running for 3 months to determine its therapeutic effects on cognitive impairment in an AD model." (PMID 35123512, 2022). "Qi-Fu-Yin can regulate the bacteria such as Bacteroidetes and Rikenellaceae related to the pathophysiological and cognitive impairment in APP/PS1 transgenic mice, thus acting as an anti-aging and improving cognition." (PMID 36710967, 2022). "CA administration reduced β-amyloid (Aβ) deposition and ameliorated cognitive impairment in APP/PS1 mice." (PMID 35393391, 2022). "Honokiol also downregulated BACE1, lowered Aβ deposition, suppressed neuroinflammation, and improved cognitive impairment in APP/PS1 transgenic mice." (PMID 35052635, 2022). "Here, we provide evidence that LPD is a novel PPARγ agonist and ameliorates cognitive deficits through PPARγ-dependent enhancement of mitophagy and glucose metabolism in the hippocampus of APP/PS1 mice." (PMID 36217155, 2022). "As a result, rhein significantly reduced Aβ burden and neuroinflammation and eventually ameliorated cognitive impairment in APP/PS1 mice." (PMID 35360200, 2022). "The AppNL-G-F mouse model expresses APP at wild-type levels, producing a robust increase in Aβ levels at 2 months of age and showing cognitive impairment starting at 6-months-of-age32." (PMID 35314851, 2022). "The major risk factor for AD is age, and it is therefore not surprising that the pathology in, for example, transgenic mouse models expressing mutant forms of APP and Tau progresses with age, as does the ensuing cognitive impairment." (PMID 35741660, 2022). "Consistent with the results of the Morris water maze tests, the results of Y-maze tests showed that the cognitive impairment in APP/PS1 mice was significantly ameliorated by eriodictyol treatment." (PMID 35093024, 2022). "Brain-derived neurotrophic factor (BDNF) is well known as a beneficial marker for cognition; its deficit contributes to cognitive disorders and results in APP fragmentation." (PMID 36040555, 2022).
Cognitive impairment (continued). "Taken together, these findings demonstrate that RH accelerates the progression of AD-type pathologies and cognitive deficits in STZ-induced APP/PS1-DM mice by inhibiting GLUT3-mediated glucose uptake." (PMID 35077394, 2022). "Reduced hippocampal neurogenesis induced by nestin deficiency, a cell proliferation marker, aggravates memory and cognitive deficits in APP/PS1 mice." (PMID 35956303, 2022). "Reactive astrocytes can be observed in the brains of patients with mild cognitive impairment in the early stages of AD, as well as in APP/PS1 mice, and precede the appearance of amyloid plaques." (PMID 36291714, 2022). "These mice (eg, APP/PS1 or E4FAD transgenic mice) are able to develop alterations in the brain typical for AD together with cognitive impairment." (PMID 35244967, 2022). "Supplementation with NAD+ precursors in animal models of AD can inhibit Aβ and tauopathies, increase the activity of PI3K-AKT and MAPK/ERK1/2 via NAD+-dependent SIRT1 and SIRT3, and eventually reverse cognitive impairment in 3 × Tg and APP/PS1 models." (PMID 36325189, 2022). "In the early stage of AD, upregulation of Treg levels can restore the cognitive impairment of APP/PS1 mice by promoting microglial phagocytosis of Aβ." (PMID 36159817, 2022). "Improved cognitive impairment and reduced plaque deposition have been observed in APP/PS1 mice after oral administration of sitagliptin for 8 weeks." (PMID 36497027, 2022). "Another study showed that DGSYS ameliorated oxidative stress and inflammation by decreasing the levels of PEG2, TXB2, and LTB4 and inhibiting the expression of cPLA2, COX-1, and COX-2, thus ameliorating cognitive deficits in APP/PS1 mice." (PMID 35164167, 2022). "The mechanisms underpinning the effects of insulin resistance on cognitive impairment include those affecting hippocampal plasticity, APP metabolism, increased tau protein concentrations, and neuroinflammation." (PMID 35615716, 2022). "The APP mouse is a great model of AD for studying the amyloidopathy since mice display cognitive impairment at 6 months of age." (PMID 35883683, 2022). "A significant correlation between NOX activity and cognitive impairment was also observed in humanized APP × PS1 mice, an animal model of AD." (PMID 36012298, 2022). "In conclusion, LPD ameliorated cognitive deficits by enhancing brain glucose uptake through activation of PPARγ-dependent mitophagy in APP/PS1 mice." (PMID 36217155, 2022). "Expressions of APP and Aβ has been shown to be increased in neuroinflammation and to be involved in cognitive impairment." (PMID 35682823, 2022). "Because global SWA is known to be disrupted in patients with AD and in fAD mouse models after the onset of cognitive decline, we used EEG/EMG recordings to test how global SWA is affected in APP/PS1 mice before robust cognitive impairments are evident." (PMID 35045289, 2022). "miR-181a negatively targets forkhead box protein O1 (FOXO1), decreasing amyloid plaque deposition in the hippocampus and cortex, mitigating pericyte loss and BBB disruption in APP/PS1 mice, and ameliorating cognitive impairment in mice." (PMID 36291714, 2022). "In NRF2-deficient mice, the levels of insoluble p-tau and Aβ increased significantly, which aggravated cognitive impairment in APP/PS1 mice." (PMID 35935875, 2022). "We demonstrated that long-term treatment with ECH improved the cognitive impairment of APP/PS1 mice by decreasing Aβ production, oxidative stress, and inflammation responses." (PMID 35665898, 2022). "Another study used high-frequency stimulation of the thalamus in TgCRND8 mice, another model of AD that expresses fivefold higher APP levels resulting in early plaque formation combined with cognitive deficits, and reported improved short-term memory." (PMID 36232336, 2022).
Cognitive impairment (continued). "A common mouse model, the APP/PS1 mouse, expresses the Swedish mutation of APP together with the ΔE9 truncated mutation of PS1, resulting in cognitive impairment despite reduced γ-secretase activity." (PMID 35449212, 2022). "On the other hand, the APP/PS1 mouse model does have the advantage of recapitulating most of the deficits associated with AD in humans, such as sleep deficits, cognitive impairment, and inflammation, phenotypes that are also seen when sleep is impaired." (PMID 37193408, 2022). "Intragastric administration of LPD for 3 months dose-dependently reversed cognitive deficits in APP/PS1 mice." (PMID 36217155, 2022). "Overall, these data confirmed that capsaicin-rich diets can rescue impairments and cognitive disorders in APP/PS1 mice." (PMID 36615777, 2022). "Their research showed that β-caryophyllene prevented cognitive impairment in APP/PS1 mice by reducing the β-amyloid burden in both the hippocampus and the cerebral cortex." (PMID 35164167, 2022). "In the mouse model, fat-rich animals induce APP/PS1xdb/db deposition, whereas ketone bodies improve cognitive impairment function." (PMID 36497027, 2022). "This is probably due to enhanced expression of NEP and TTR by SUMOylated AICD, resulting in more efficient clearance of Aβ; therefore, less severe pathology and cognitive impairment were observed in APP/PS1 mice." (PMID 32950104, 2021). "Our findings indicate that microinfarcts reduced Aβ deposits without affecting soluble Aβ levels in the brain of male and female APP/PS1 mice, while causing rapid and prolonged cognitive deficits in males, and a mild and transient cognitive decline in females." (PMID 35173711, 2021). "In conclusion, we suggest that Dihexa rescues cognitive impairment and recovers memory by ameliorating neuronal loss and inhibiting inflammation and glial activation via PI3K/AKT signaling pathways in APP/PS1 mice." (PMID 34827486, 2021). "Environmental stress increased glucocorticoid levels, AD-like neuropathology, and cognitive impairments in APP/PS1 mice, implying that EOAD model mice are more vulnerable to environmental stress than WT mice." (PMID 33407614, 2021). "This cognitive impairment measured by Y-maze of APP/PS1 mice fed a ZD diet for 3 months was reversed by returning the mice to a ZN diet for 3 months (Z = −3.93, p < 0.001)." (PMID 33597269, 2021). "CuGTSM has a much lower affinity for Cu2+ compared with CuATSM yet was far more potent than CuATSM in rescuing cognitive impairment in APP/PS1 transgenic mouse model." (PMID 33219130, 2021). "The results show that treatment of APP/PS1 mice with geniposide can not only improve cognitive deficits but also reduce amyloid-β 1-40 (Aβ1-40) plaque deposition and reduce soluble Aβ1-40 and Aβ1-42 in APP/PS1 mice." (PMID 34454545, 2021). "Our data provide evidence that the onset of cognitive impairment in the APP/PS1 mouse model was dramatically accelerated after mTBI." (PMID 34539542, 2021). "In rodent studies of DS-AD, triplication of chromosome 21 genes other than APP demonstrated increased Aβ aggregation deposition and cognitive deficits." (PMID 34744690, 2021). "Microvascular ultrastructural changes in brain of APP/PS1 AD model mice have been reported to precede cognitive impairment." (PMID 34479211, 2021). "Our results showed that EVs treatment improved their behavioral performances including learning, memory, and recognition compared to the saline group, suggesting that the positive therapeutic effects of MSC-EVs on cognitive deficits in APP / PS1 mice." (PMID 34482379, 2021). "Here we treated APP/PS1 AD mice with a therapeutic dose of memantine (20 mg/kg/day) and examined its underlying mechanisms in ameliorating cognitive defects." (PMID 34120588, 2021). "Results above suggested that thioperamide improved the cognitive impairments in APP/PS1 Tg mice in vivo." (PMID 33682314, 2021).
Cognitive impairment (continued). "Ligature-induced periodontitis in rats resulted in systemic inflammation and further abnormal APP processing, leading to cognitive impairments." (PMID 33757547, 2021). "The latest research showed that long-term TSG (50, 100 mg/kg) treatment significantly improved the cognitive impairment by reducing the deposition of Aβ plaques in the hippocampus and cortex in the APP/PS1 AD mouse model, thereby preventing AD." (PMID 35069206, 2021). "Taken together, these results suggested that H3R antagonist thioperamide improved cognitive impairment in APP/PS1 Tg mice via modulation of the CREB‐mediated autophagy and lysosomal pathway, which contributed to Aβ clearance." (PMID 33682314, 2021). "In the present study, berberine was shown to ameliorate ER stress and cognitive impairment in APP/PS1 mice." (PMID 34349640, 2021). "Diosmin treatment effectively ameliorated the cognitive disorder and memory deficit of APP/PS1 transgenic mice." (PMID 34522212, 2021). "In conclusion, we determined that DLT effectively improved cognitive impairment in APP/PS1 mice by improving microglial dysfunction." (PMID 33369003, 2021). "The STAT3 signaling pathway was activated in this progress, which further resulted in abnormal APP processing and cognitive impairment." (PMID 33757547, 2021). "As α- and β-secretases are commonly activated competitively in the APP-cleavage process, this competition can control the Aβ accumulation and alleviate the cognitive impairment in AD." (PMID 33652858, 2021). "In conclusion, this study demonstrated that curcumin treatment significantly ameliorates cognitive impairment in aged APP/PS1 transgenic mice." (PMID 34405526, 2021). "Animal studies have suggested that dl-3-n-butylphthalide (dl-NBP) alleviates cognitive impairment in mouse models of APP/PS1 and SAMP8." (PMID 33642981, 2021). "Studies have shown that platelet APP ratio (representing the percentage of 120–130 kDa to 110 kDa isoforms of the amyloid precursor protein) is reduced in patients with mild cognitive impairment (MCI) and Alzheimer's disease (AD)." (PMID 33824766, 2021). "6D11 attenuated cognitive deficits in APP/PS1 transgenic mice, which was accompanied by a decrease of the deposition of Aβ." (PMID 34672433, 2021). "In an attempt to evaluate the capability of DLT in ameliorating memory and cognitive impairments of APP/PS1 mice, the models of new object recognition, Y‐maze, and Morris water maze were applied (for each test, n = 8)." (PMID 33369003, 2021). "Metabolic alterations, including deficits in acylcarnitines, have previously been reported in brains of a transgenic mouse model of AD bearing mutated APP and PS1 transgenes, in which early brain amyloid deposition and cognitive impairment occur." (PMID 34228639, 2021). "The Barnes maze test also indicated that RFP rescued the exacerbated cognitive impairment in MITOL-deleted APP/PS1 mice." (PMID 33580194, 2021). "Our data indicate that APP mice have cognitive impairment along with elevated amyloid β, tau proteins, and caspase-3." (PMID 34046506, 2021). "It has been reported that APP/PS1 mice show amyloid deposition at 2 months of age, amyloid plaques at 5 months of age, synaptic loss after 7–9 months, and severe cognitive impairment." (PMID 34975476, 2021). "Together, these results indicate that MSC-EVs treatment improves the cognitive deficits observed in APP / PS1 mice." (PMID 34482379, 2021). "OB has been reported to mitigate the cognitive impairments in APP/PS1 mice, aging rats induced by D-galactose, as well as LPS-injured rats." (PMID 34696749, 2021). "APP/PS1 transgenic mouse model has been well characterized for cognitive impairment, with the reduction of transient long-term potentiation by 3 months of age." (PMID 33409475, 2021).
Cognitive impairment (continued). "In conclusion, we demonstrated that the H3R antagonist thioperamide improved cognitive impairment in APP/PS1 mice via modulation of the CREB‐mediated autophagic and lysosomal pathway, which contributed to Aβ clearance." (PMID 33682314, 2021). "Microvascular ultrastructural changes in brain have also been reported to be prior to the onset of cognitive impairment in APP/PS1 AD model mice at 4 to 5 months of age." (PMID 34479211, 2021). "To detect cognitive impairment in the APP/PS1 mice, we performed Morris water maze experiments and found that sevoflurane-treated mice displayed poorer navigation and spatial skills than the control mice." (PMID 35127716, 2021). "For the two experiments above, 9-months old APP/PS1 mice were used as the positive controls, which showed a prominent cognitive impairment as compared to 6-month old APP/PS1 mice (p< 0.05)." (PMID 34658785, 2021). "Analysis of APP fragments in CSF, currently used to diagnose individuals with cognitive impairments, are thought to represent pathological changes within the brain." (PMID 34580355, 2021). "In conclusion, our findings suggest that ETAS®50 is beneficial for cognitive impairments, reduction of Aβ deposition, and hyperphosphorylation of tau protein in young transgenic mice overexpressing APP." (PMID 34046506, 2021). "Our results show that APP-overexpressing mice encountered cognitive impairment while treatment with ETAS®50 significantly restored cognitive function using the Morris Water Maze." (PMID 34046506, 2021). "NSAIDs prevented cognitive impairment in APP/PS1 AD mice, independently from Aβ levels or Iba1-positive microglial activation effects." (PMID 32917871, 2020). "OLT data revealed that EpoD treatment protected from the cognitive deficits observed in vehicle-injected APP/PS1 group (p < 0.01)." (PMID 32901091, 2020). "The decrease of nuclear YAP due to cytoplasmic co-segregation with Aβ was confirmed in cortical neurons of 5xFAD mice and human mutant APP-KI mice at 3 months, prior to the onset of cognitive impairment." (PMID 31980612, 2020). "To confirm that the APP/PS1 animal model used in this study shows cognitive impairments at the time point of choice (9 mo of age), we performed behavior tests." (PMID 33257576, 2020). "Taken together, these results clearly indicated that CPPs treatment significantly attenuated cognitive deficits in APP/PS1 mice." (PMID 32652518, 2020). "Taken together, all these data indicated that EpoD treatment prevented the onset of hippocampal-related cognitive impairment in APP/PS1 mice." (PMID 32901091, 2020). "The study showed that the 2‐week rTMS at 5Hz frequency improved cognitive impairments and AD‐like pathology (including a decrease in p‐Tau, APP, Aβ, and PP2A expression) of APP/PS1 mice." (PMID 32592331, 2020). "Firstly, we determined the effect of GLTs on cognitive disorder in APP/PS1 transgenic AD model mice compared to the control normal mice by place navigation test and spatial probe test." (PMID 32089787, 2020). "In comparison to controls, the APP levels are lower in mild cognitive impairment and in mild and moderate AD, while high levels of APP characterize severe AD." (PMID 33362690, 2020). "We previously reported that Klotho lowered Aβ levels in the brain and protected against cognitive deficits in amyloid precursor protein/presenilin 1(APP/PS1) mice." (PMID 32964663, 2020). "We have recently showed that Cef can stimulate GLT-1 expression and improve cognitive impairment in APP/PS1 AD mice." (PMID 33132901, 2020). "In comparison with wild-type mice, APP/PS1 mice exhibited significant cognitive deficits, represented with poor performance in novel object recognition and Morris water maze tests, downregulated GLT-1 expression and glutamate uptake." (PMID 33132901, 2020).